GSTP1 (glutathione S-transferase pi 1)
Diseases named in the same sentence as GSTP1 in open-access papers (continued):
Sharing a sentence is not in itself a finding about the gene and the disease.
malnutrition (1 paper, 2025). Inadequate nutrition resulting from poor diet, malabsorption, or abnormal nutrient distribution. "Higher methylation levels of LINE-1 at its CpG1 site and GSTP1 were also found in the patients with severe malnutrition." (PMID 40284160, 2025). "A significant association was observed between DNA methylation levels of the D-loop, GSTP1, and the CpG1 site of LINE-1 and malnutrition, disease progression at diagnosis, and death." (PMID 40284160, 2025). "When the DNA methylation levels of the selected markers (D-loop, GSTP1, and LINE-1) were evaluated, statistically significant differences were found in relation to malnutrition, disease progression, and death." (PMID 40284160, 2025). "On the other hand, regarding GSTP1 and LINE-1 at its CpG1 site, higher methylation levels were found in the patients with severe malnutrition, with GSTP1 showing a tendency toward greater differences the greater the severity of malnutrition." (PMID 40284160, 2025).
medulloblastoma (1 paper, 2019). A malignant, invasive embryonal neoplasm arising from the cerebellum. "The GSTP1 “Val” allele was associated with ototoxicity in patients with medulloblastoma who were treated with CDDP-based therapy." (PMID 31249357, 2019).
mucinous adenocarcinoma (1 paper, 2005). An invasive adenocarcinoma composed of malignant glandular cells which contain intracytoplasmic mucin. "Longer patient follow-up and standardised treatment will be required to fully explore the role of TYMS and GSTP1 overexpression in mucinous adenocarcinoma." (PMID 15655543, 2005).
nasopharyngeal carcinoma (1 paper, 2010). A carcinoma arising from the nasopharyngeal epithelium. "Over 200 studies have investigated the association between the polymorphism of GSTP1 and different cancers, however only one study analyzed this gene region for nasopharyngeal carcinoma." (PMID 20663217, 2010). "Although numerous studies have examined the association of the polymorphisms for CYP2E1, GSTP1, MPO and NQO1 genes with various tumors, very few have investigated the associations between variants of these genes and the risk of nasopharyngeal carcinoma." (PMID 20663217, 2010).
nicotine dependence (1 paper, 2022). Physical and psychological dependence on nicotine. "On the other hand, GSTP1 was predominant among benign lesions and significantly correlated smoking parameters such as number of cigarettes smoked per day, duration of tobacco consumption, and nicotine dependence assessed by TFCD, providing a probable protective action to smokers." (PMID 35409669, 2022).
non-small cell lung adenocarcinoma (1 paper, 2023). Type of epithelial lung cancer arising from glandular origin. "The in vitro studies of these covalent inhibitors showed a prolonged inactivation of the GSTP1-1 in human non-small-cell lung adenocarcinoma cells, which served as lead compounds for the further development of potent inhibitors of GSTP1-1 in cancer." (PMID 37189435, 2023).
nonalcoholic fatty liver (1 paper, 2020). "For example, in one study, GSTM1-null and GSTP1 Val allele genotypes, were found to increase the risk of nonalcoholic fatty liver in the Iranian population." (PMID 33083304, 2020).
oral cavity cancer (1 paper, 2012). A primary or metastatic malignant neoplasm involving the oral cavity. "If there is association between the GSTP1 Ile105Val polymorphism and the risk of oral cavity cancer or oropharyngeal cancer still remains unclear, although it is negative as combined subset according to our results." (PMID 23144854, 2012). "Studies on GSTP1 polymorphism and the risk of oral cavity cancer reached controversial conclusions." (PMID 23144854, 2012).
oropharyngeal cancer (1 paper, 2012). Carcinoma, predominantly squamous cell, arising from the epithelial cells of the oropharynx. "In this study, no positive association was found between the GSTP1 polymorphism and the risk of oral or oropharyngeal cancer." (PMID 23144854, 2012).
Peri-Implantitis (1 paper, 2019). An inflammatory process with loss of supporting bone in the tissues surrounding functioning DENTAL IMPLANTS. "Three leader genes (PSMD10, SOS1, WASF3), eight cross-talk genes (PSMD10, PSMD6, EIF2S1, GSTP1, DNAJC3, SEC61A1, MAPT, and NME1), and one signaling pathway (IL-17 signaling) emerged as peri-implantitis and T2DM linkage mechanisms." (PMID 31275749, 2019).
polyposis (1 paper, 2019). "Next, we performed the overall analysis involving 298 cases and 477 controls for the association between the GSTP1 Ile105Val polymorphism and polyposis susceptibility." (PMID 30617052, 2019).
psychostimulant addiction (1 paper, 2019). "Moreover, GSTP1 polymorphisms have been linked to human psychostimulant addiction in two distinct populations, and inhibiting GSTP in rodents augments locomotion in a behavioral sensitization model of cocaine-induced neuronal plasticity." (PMID 31550273, 2019).
pulmonary sarcoidosis (1 paper, 2025). Sarcoidosis affecting the lung parenchyma. "Moreover, GSTP1 has been recognized as a central node in the functional enrichment analysis of proteomics in pulmonary sarcoidosis." (PMID 41279897, 2025).
salivary gland tumors (1 paper, 2024). "Some of the identified peptides were derived from proteins previously suggested as potential biomarkers of salivary gland tumors (ANXA1, BPIFA2, FGB, GAPDH, HSPB1, IGHG1, VIM) or tumors of other tissues or organs (SERPINA1, APOA2, CSTB, GSTP1, S100A8, S100A9, TPI1)." (PMID 39201484, 2024).
skin toxicities (1 paper, 2006). "Low activity GSTP1 genotypes were associated with a greater than twofold increase in risk for acute skin toxicities (adjusted hazard ratio 2.28, 95% confidence interval 1.04–4.99)." (PMID 16848913, 2006).
skin ulceration (1 paper, 2020). "A significant correlation was confirmed between GSTP1 polymorphism and toxicity like vomiting and skin ulceration strengthening GSTP1 polymorphism as a predictor of severe events." (PMID 33280607, 2020). "GSTP1 was determined to be an independent risk factor for severe vomiting and skin ulceration (p = 0.042 and p = 0.018, respectively)." (PMID 33280607, 2020).
sleep disorder (1 paper, 2025). A change from the patient's baseline sleeping pattern, in the hours slept and/or an alteration/dysfunction in the stages of sleep. "GSH and GSTP1 are associated with some gut microbiome markers in menopausal women, but these relationships differ in different sleep disorders." (PMID 41562844, 2025).
thyroid cancer (1 paper, 2008). "Variations in GSTT1, GSTM1 and GSTP1 have been previously demonstrated to influence drug efficacy and toxicity and also to modify individual susceptibility to cancers however, there are scarce data specific to patients with thyroid cancer." (PMID 18601742, 2008). "Although GSTP1 C2293T, genotype TT accounted for 5% of PTC cases comparing with 1.5% of controls and showed 3.24 fold higher risk to develop thyroid cancer but did not reached to level of significance." (PMID 18601742, 2008).
Tinnitus (1 paper, 2007). Tinnitus is an auditory perception that can be described as the experience of sound, in the ear or in the head, in the absence of external acoustic stimulation. "After cisplatin-based chemotherapy, the risk of self-reported peripheral paresthesias, Raynaud-like phenomena in the toes, and tinnitus is halved in TCSs homozygous for GSTP1-G compared to those with GSTP1-AA/AG." (PMID 18162130, 2007). "GSTP1-GG proved highly protective against chemotherapy-induced tinnitus (OR = 0.33)." (PMID 18162130, 2007). "Compared to TCSs with either GSTP1-AG or GSTP1-AA, the 37 TCSs with the genotype GSTP1-GG, were significantly less bothered by paresthesias in fingers and toes (p = 0.039, OR 0.46 [0.22–0.96] and p = 0.023, OR 0.42 [0.20–0.88], respectively), and tinnitus (p = 0.008, OR 0.33 [0.14–0.74])." (PMID 18162130, 2007).
vitiligo (1 paper, 2019). Generalized well circumscribed patches of leukoderma that are generally distributed over symmetric body locations and is due to autoimmune destruction of melanocytes. "Moreover, KBL was found to modulate vitiligo via the regulation of activity of multiple series enzymes such as tyrosinase (TYR), oxidoreductase (GSTP1, CAT, MPO, and GSTM1), and controlling signal transducer (NFE2L2)." (PMID 31781265, 2019).
Vogt-Koyanagi-Harada syndrome (1 paper, 2024).
cancer (347 papers, 1993 to 2026). A tumor composed of atypical neoplastic, often pleomorphic cells that invade other tissues. "Beyond its canonical role in detoxification, GSTP1 has also been implicated in cancer cell metabolism, apoptotic signaling, and drug resistance." (PMID 40719618, 2025). "GSTP1 gene hypermethylation has been implicated in various cancers, including HCC, as a potential biomarker for diagnosis, prognosis, and therapeutic strategies." (PMID 40051701, 2025). "While GSTP1 depletion has been associated with decreased cancer growth in various models, the mechanism remains poorly understood." (PMID 40719618, 2025). "GSTP1 has been shown to protect pancreatic cancer cells from radiation-induced ferroptosis and its overexpression is associated with increased cancer risk, particularly in OS." (PMID 41301848, 2025). "This study investigates the inhibitory potential of telomere-targeted compounds, specifically 6-thio-dG and its dimer form, on GSTP1, a key enzyme implicated in cancer progression and chemoresistance." (PMID 39954068, 2025). "In cancer, GSTP1 has been implicated in tumorigenicity, cell cycle progression, and chemoresistance." (PMID 40719618, 2025). "Given the pivotal role of immune responses not only in PCOS but also in cancer pathogenesis, we employed GSTP1 and LPCAT1 to investigate potential associations between these two disease categories." (PMID 40555906, 2025). "The emerging evidence on the role of SMURF2 in modulating ferroptosis by mediating the degradation of glutathione S-transferase P1 (GSTP1) dismantles a key defense against ferroptosis, thereby predisposing cancer cells to this unique form of cell death." (PMID 39697237, 2024). "It has been suggested that understanding the correlation between GSTP1 Ile105Val polymorphisms and responses to GSTP1-1 inhibitor treatment would offer valuable insights for future drug development targeting GSTP1 in cancer-related diseases." (PMID 39125992, 2024). "GSTP1 levels are associated with multiple human pathologies including multiple aggressive cancers, and over-expression is known to result in drug resistance." (PMID 39269939, 2024). "The aim of this study was to draw a latest conclusion on the relationship between GSTM1, GSTT1 and GSTP1 gene polymorphism and cancer risks among smokers and drinkers." (PMID 38579033, 2024). "Broader sample data and appropriate experimental design were needed to further investigate the effects of GSTM1, GSTT1 and GSTP1 polymorphisms on cancer among smokers or drinkers." (PMID 38579033, 2024). "In fact, it has been indicated that the Ile105Val polymorphism of GSTP1 exhibits the highest expression in lung tissue and is associated with several cancer types." (PMID 38673753, 2024). "The SNPs in the genes encoding GSTs that are studied to stratify the risk of development of this cancer, most often are focused on GSTP1 gene, of which rs1695 and rs1138272 are the most common variants of this gene." (PMID 37819495, 2023). "Overexpression of GST, particularly GSTP1-1, has been linked to innate and acquired resistance to anticancer drugs, indicating that cancer cells utilize the GSH-binding activity of GST to evade the effects of these drugs." (PMID 37047688, 2023). "In the context of cancer, GSTP1 has been associated with susceptibility to certain tumors and responsiveness to chemotherapy drugs." (PMID 37735436, 2023). "The meta-analysis conducted in 2012 was found that GSTM1 null genotype, GSTM1 and GSTT1 double null genotype or GSTT1 null genotype and rs1695 polymorphism within the GSTP1 gene can correlate with an increased risk of cancer development." (PMID 37819495, 2023). "Many studies have confirmed that the expression level of GSTP1 is associated with an increased risk of various cancers." (PMID 36589232, 2022).
cancer (continued). "The epigenetic regulation of GSTM2 has been associated with several cancers, among which is PCa, although there are far less studies compared to GSTP1, and far more variable findings in the context of proteomics PCa studies." (PMID 36553191, 2022). "GSTP1 variants have been linked to toxic effects and unwanted outcomes of anti-cancer drugs, especially platinum agents." (PMID 35505645, 2022). "The GSTP1 is frequently inactivated in BC and other cancers, whereas its polymorphisms have been associated with elevated BC risk." (PMID 37082114, 2022). "In terms of association with other molecular alterations, GSTP1 positivity was enriched in ERG positive cancers among Black men." (PMID 34191807, 2021). "It was concluded that doxorubicin-resistant cancer cells are susceptible to drug treatment if treated with GSTP1 inhibitors such as NBDHEX." (PMID 33946704, 2021). "The highest level of GSTP1 activity is seen in individuals with the AA genotype (Ile/Ile) and is associated with increased toxicity in different carcinomas, but there are discordant results regarding the effect of GSTP1 c.313A>G on treatment outcomes." (PMID 33326171, 2021). "The GSTP1 gene encodes active, functionally different proteins that play a role in susceptibility to cancer and other diseases via regulation of xenobiotic metabolism." (PMID 33615312, 2020). "The significance of another GSTP1*Ala114Val rs1138272 polymorphism in cancer susceptibility has emerged recently." (PMID 32183092, 2020). "Actually, the scientific literature about the GSTP1 polymorphisms and cancer is extremely abundant, in this respect here we only report a few examples for a restricted number of common types of tumors." (PMID 31357662, 2019). "GSTP1-1, which is actively involved in the detoxification of cisplatin, has been implicated as a predictive marker of overall survival in cancer patients receiving cisplatin-based chemotherapy." (PMID 31357662, 2019). "GSTP1-1 usually is highly expressed in proliferating cells than in the differentiated cells and this elevated expression is associated with the cancer progression and therapy resistance." (PMID 31357662, 2019). "The level of heterogeneity and publication bias was reduced in the analyses of the Caucasian population, suggesting that the “ethnicity” factor is essential for the assessment of the distinct role of GSTP1 rs1138272 in cancer risk." (PMID 30740061, 2018). "First, we analyzed the relationship between the GSTP1 rs1138272 polymorphism and the risk of cancer through a meta-analysis of the overall population." (PMID 30740061, 2018). "We detected a potential correlation between the TT genotype of GSTP1 rs1138272 and cancer susceptibility in the Asian population, which is partly in agreement with the previously reported data." (PMID 30740061, 2018). "In view of the publication of new relevant articles in the last 5 years, we performed an updated meta-analysis to gain insight into the genetic association between the rs1138272 C/T polymorphism of the GSTP1 gene and the risk of cancer." (PMID 30740061, 2018). "There have been several comprehensive analyses concerning the potential role of the GSTP1 rs1695 polymorphism in the susceptibility to cancer." (PMID 30740061, 2018). "In particular, GSTT1-1 and GSTM1-1 null genotypes, as well as GSTP1-1 variants, were studies and showed a positive correlation with cancer risk 24,32,35–42." (PMID 29362397, 2018). "Considering the role of possible linkage disequilibrium in the genetic susceptibility to different cancers, we tried to extract the data of GSTP1 haplotypes in the enrolled case-control studies." (PMID 30740061, 2018). "The limited availability of useable data also prevented us from exploring the genetic effects of the GSTP1 polymorphism combined with variants of other genes in specific cancer types." (PMID 30740061, 2018).